CR1L (complement C3b/C4b receptor 1 like)
Tractability: Antibody: UniProt places it where antibodies can reach, with high confidence; UniProt predicts a signal peptide or a membrane-spanning region; its Gene Ontology location is reachable by antibodies, with medium confidence. PROTAC: its protein half-life has been measured.
Gene: Protein-coding gene on chromosome 1 (207,645,113 to 207,738,416, forward strand). Ensembl gene ENSG00000197721.
Subcellular location: Cytoplasm; Membrane; Secreted
Gene Ontology:
Molecular function: protein binding
Biological process: regulation of complement activation; regulation of complement-dependent cytotoxicity; negative regulation of complement activation, classical pathway; T cell mediated immunity
Cellular component: receptor complex; plasma membrane; cytoplasm; extracellular region; membrane
Genetic constraint (gnomAD): Loss-of-function variants: 56 observed, 60.07 expected, observed/expected ratio (o/e) 0.93, 90% interval 0.75 to 1.16. The upper end of that interval is the gene's LOEUF score, 1.16, which puts it in group 5 of 6, group 1 being the genes least tolerant of losing a copy. Missense variants: 674 observed, 695.09 expected, observed/expected ratio (o/e) 0.97, 90% interval 0.91 to 1.03. Synonymous variants: 272 observed, 247.52 expected, observed/expected ratio (o/e) 1.1, 90% interval 0.99 to 1.22.
Homologues: Orthologues: chimpanzee CR1L (96% identical), macaque CR1L (88% identical). Paralogues in human: CR1 (75% identical), CSMD3 (27% identical), CSMD1 (25% identical), CR2 (25% identical), CSMD2 (24% identical), SVEP1 (23% identical), C4BPA (19% identical), SELP (16% identical), CD46 (16% identical), SEZ6 (15% identical), CFH (15% identical), SEZ6L (15% identical), and 27 more.
Diseases named in the same sentence as CR1L in open-access papers:
CR1L is named in the same sentence as 10 diseases in open-access papers, as found by Europe PMC text mining. Sharing a sentence is not in itself a finding about the gene and the disease. The quoted sentences say what the papers report.
Alzheimer disease (3 papers, 2019 to 2022). A progressive, neurodegenerative disease characterized by loss of function and death of nerve cells in several areas of the brain leading to loss of cognitive function such as memory and language. "For the CD46 locus, we found significant association corrected for multiple testing (false-discovery rate, FDR < 5%) for schizophrenia (in CD46 and CR1L) and for Alzheimer’s disease (in CR1)." (PMID 32843070, 2020).
schizophrenia (2 papers, 2020 to 2024). A major psychotic disorder characterized by abnormalities in the perception or expression of reality. "It is worth noting that three of our potential candidate genes for depressive episodes have previously shown associations with either major depression at the gene-level (DCC) or mapped to schizophrenia loci (CR1L and DGKI) in large GWASs." (PMID 38570518, 2024).
epilepsy (1 paper, 2015). A brain disorder characterized by episodes of abnormally increased neuronal discharge resulting in transient episodes of sensory or motor neurological dysfunction, or psychic dysfunction. "Also little is known about the specific functional implications of the downregulated complement factors C1qa (0.88-fold) and Cr1l (0.91-fold) in epilepsy." (PMID 26684451, 2015).
liver diseases (1 paper, 2024). "The negative correlation with key inflammatory cytokines, notably those involved in acute and chronic inflammatory responses and liver diseases, like IL-1β, IL-18, and TNF-α, reinforces the hypothesis that CR1L might have a protective role in AH." (PMID 38573776, 2024).
infection (1 paper, 2025). The state of being infected such as from the introduction of a foreign agent such as serum, vaccine, antigenic substance or organism. "These include murine genes incompatible with HCV biology (CD81, OCLN, TRIM26, CypA) and those murine factors that actively inhibit infection (CD302, CR1L)." (PMID 40899815, 2025).
CR1L also shares sentences with these, for which no sentence is quoted: epidermolysis bullosa (1 paper); major depression (1); measles (1); rheumatoid arthritis (1); tumor (1).